LRP2BP (LRP2 binding protein)
Description:
May act as an adapter that regulates LRP2 function.
Synonyms: DKFZp761O0113
Tractability: No criterion of Open Targets' tractability assessment is met for any kind of drug.
Gene: Protein-coding gene on chromosome 4 (185,363,655 to 185,397,288, reverse strand). Ensembl gene ENSG00000109771.
Subcellular location: Cytoplasm
Subcellular location (Human Protein Atlas): Golgi apparatus
Gene Ontology:
Molecular function: protein binding
Cellular component: cytoplasm
Genetic constraint (gnomAD): Loss-of-function variants: 24 observed, 29.94 expected, observed/expected ratio (o/e) 0.8, 90% interval 0.58 to 1.13. The upper end of that interval is the gene's LOEUF score, 1.13, which puts it in group 4 of 6, group 1 being the genes least tolerant of losing a copy. Missense variants: 296 observed, 341.62 expected, observed/expected ratio (o/e) 0.87, 90% interval 0.79 to 0.95. Synonymous variants: 116 observed, 126.38 expected, observed/expected ratio (o/e) 0.92, 90% interval 0.79 to 1.07.
Homologues: Orthologues: chimpanzee LRP2BP (99% identical), macaque LRP2BP (96% identical), pig LRP2BP (93% identical), dog LRP2BP (91% identical), rabbit LRP2BP (90% identical), guinea pig LRP2BP (89% identical), rat Lrp2bp (87% identical), mouse Lrp2bp (86% identical), tropical clawed frog lrp2bp (56% identical), zebrafish lrp2bp (47% identical), Caenorhabditis elegans sel-1 (19% identical). Paralogues in human: SEL1L3 (23% identical), SEL1L (22% identical), SEL1L2 (21% identical), DELE1 (16% identical).
Diseases named in the same sentence as LRP2BP in open-access papers:
LRP2BP is named in the same sentence as 5 diseases in open-access papers, as found by Europe PMC text mining. Sharing a sentence is not in itself a finding about the gene and the disease. The quoted sentences say what the papers report.
atherosclerosis (2 papers, 2012 to 2022). A disease characterized by the build-up of fatty material and calcium deposition in the arterial wall resulting in partial or complete occlusion of the arterial lumen. "Among the lncRNAs that suppress VSMC migration, lncRNA RP11-714G18.1 acts by directly targeting LDL-related receptor 2 binding protein (LRP2BP) in atherosclerosis." (PMID 35328769, 2022). "Furthermore, lncRNA RP11-714G18.1 impairs VSMC migration in atherosclerosis through the LRP2BP-mediated downregulation of MMP1." (PMID 35328769, 2022). "The LRP2BP and LRP1B genes are two members of the low-density lipoprotein receptor family that participates in a wide range of physiological processes, including the regulation of lipid metabolism, protection against atherosclerosis, neurodevelopment, and transport of nutrients and vitamins." (PMID 23241142, 2012).
behavioral disorders (2 papers, 2017 to 2025). "In addition, differentially methylated CG dinucleotides in LRP2BP, TOP1, NOSIP, and SEMA4B were associated with intellectual disability, behavioral disorders, disorders of psychological development, and schizophrenia spectrum disorders, respectively." (PMID 39460848, 2025).
LRP2BP also shares sentences with these, for which no sentence is quoted: disorders of psychological development (2 papers); Intellectual disability (2); developmental delay (1).